ASPG (asparaginase)
Diseases named in the same sentence as ASPG in open-access papers (continued):
Sharing a sentence is not in itself a finding about the gene and the disease.
lymphoma (14 papers, 2001 to 2024). A malignant (clonal) proliferation of B- lymphocytes or T- lymphocytes which involves the lymph nodes, bone marrow and/or extranodal sites. "The most efficient regimens are broadly separated into these sub-types: acute leukemia treatment (AML or ALL-like), lymphoma-like treatment, and asparaginase/methotrexate-based treatments that are also used in aggressive leukemias and lymphomas." (PMID 35565416, 2022). "Similar observations were also recorded with asparaginase treated mouse lymphoma and human T lymphocytes cells and with other molecules recently tested as potent antileukemic agent." (PMID 26891220, 2016). "Moreover, PLP modification extends the elimination half-life of asparaginase (ASNase) 18-fold and mitigates the immunogenicity of wt ASNase >250-fold (ASNase is a first-line anticancer drug for lymphoma treatment)." (PMID 36072505, 2022). "Asparaginase (ASNase) is a first-line enzyme-based anticancer drug for acute lymphatic leukemia and several aggressive subtypes of lymphoma, but is known for its notoriously poor pharmacokinetic profiles and strong immunogenicity, which necessitates polymer conjugation." (PMID 36072505, 2022). "Arginase and asparaginase may be therapeutic in Burkitt lymphoma, but it would be important to test this in primary lymphoma cells from patients." (PMID 30578463, 2019). "This study establishes a scientific basis for long-term cold storage of reconstituted E. coli-derived asparaginase that may result in better utilization of limited drug resources and improve financial feasibility of E. coli-derived asparaginase as a therapeutic option for pets with lymphoma." (PMID 23738234, 2013). "In the group of 19 participants who reported that asparaginase levels were monitored, 68.4% reported that testing was performed in all asparaginase‐treated patients, 21.1% only in patients with ALL, and 10.5% in lymphoma patients or in other situations." (PMID 36307379, 2023). "Retrospective data imply a better rate of response with first-line therapy that includes asparaginase/MTX and in ALL-like compared to AML-like or lymphoma-like treatment." (PMID 35565416, 2022). "Effects of cold-stored asparaginase on cell proliferation and cytotoxicity were measured in feline (MYA-1, F1B) and canine (17–71, OSW) lymphoma cells." (PMID 23738234, 2013). "The rationale behind using asparaginase agents as an anti-cancer treatment is that normal lymphocytes have the asparagine synthetase enzyme and can promote the biosynthesis of their own asparagine, whereas this does not occur in lymphoma cells." (PMID 31649489, 2019).
osteonecrosis (13 papers, 2016 to 2024). A none disease characterized by death of bone tissue due to a lack of blood supply. "Two additional toxicities of asparaginase, hypertriglyceridemia and osteonecrosis, are also implicated in the setting of glucocorticoid use, another mainstay of ALL therapy." (PMID 35844739, 2022). "Evidence is accumulating that asparaginase can increase the risk of osteonecrosis." (PMID 26967741, 2016). "A multivariate analysis including plasma dexamethasone and asparaginase levels suggested that dexamethasone (OR = 1.01 for every 1 nmol/L increase, P = 0.029) and asparaginase concentrations (OR = 1.06 for every 1 IU/mL increase, P = 0.002) were both independently associated with osteonecrosis." (PMID 26967741, 2016). "Increased use of asparaginase has been postulated as potentiating the osteonecrosis effect of glucocorticoids." (PMID 35844739, 2022). "There were other genetic polymorphisms related to some common adverse effects of chemotherapy, such as vincristine neuropathy, asparaginase hypersensitivity, hypertension, and osteonecrosis due to steroid use37−45." (PMID 32873882, 2020). "Using the murine model of osteonecrosis, we compared the frequency of osteonecrosis in mice receiving discontinuous dexamethasone (3.5 days/ week) with mice receiving asparaginase and discontinuous dexamethasone." (PMID 31059548, 2019). "Here, we evaluate the addition of asparaginase to a discontinuous dexamethasone regimen and evaluate the effects on both osteonecrosis development and antileukemic efficacy using murine and human xenograft models, respectively." (PMID 31059548, 2019). "As in the osteonecrosis mice, dexamethasone concentrations were higher in mice receiving asparaginase (median 61.2 nM, IQR 32–81.5 nM) compared to mice receiving dexamethasone alone (median 19.2 nM, IQR 13.5–32.1, p = 8.5x10-4)." (PMID 31059548, 2019). "Increased rates of osteonecrosis when dexamethasone and asparaginase are combined during post-remission therapy have led to a modification of dexamethasone dosing during these periods." (PMID 31059548, 2019). "Asparaginase is known to potentiate both the antileukemic and osteonecrosis-inducing effects of dexamethasone." (PMID 31059548, 2019). "Osteonecrosis developed in 12 of 27 (44.4%) mice who received dexamethasone and asparaginase, which is significantly more frequent (P = 0.006) than in mice who received dexamethasone alone (3 of 30 or 10.0%)." (PMID 26967741, 2016). "There are several possible mechanisms for the potentiating effect of asparaginase on glucocorticoid-induced osteonecrosis." (PMID 26967741, 2016). "This animal model allows us to study the optimal dosing strategy of glucocorticoids and asparaginase, and explore the utility of new biomarkers for osteonecrosis." (PMID 26967741, 2016). "In summary, we were able to recapitulate the potentiating effect of asparaginase on glucocorticoid-induced osteonecrosis using a mouse model." (PMID 26967741, 2016). "Mice receiving asparaginase along with dexamethasone had a higher rate of osteonecrosis than those receiving only dexamethasone after 6 weeks of treatment (44% vs. 10%, P = 0.006)." (PMID 26967741, 2016). "Here we utilized a mouse model to study the effect of asparaginase treatment on dexamethasone-induced osteonecrosis." (PMID 26967741, 2016). "Intensive ALL treatment schedules including corticosteroids and asparaginase have been shown to give rise to skeletal abnormalities such as osteonecrosis and low bone mineral density (BMD), which may lead to debilitating sequelae in survivors." (PMID 34308423, 2021). "This, combined with our prior work demonstrating the combination of asparaginase and continuous dexamethasone increases osteonecrosis, suggests that the deleterious interaction between asparaginase and dexamethasone on the development of osteonecrosis is schedule dependent." (PMID 31059548, 2019).
osteonecrosis (continued). "Similarly, epiphyseal arteriopathy, which we have shown to be an initiating event for osteonecrosis, was observed in 58% of mice receiving asparaginase and dexamethasone compared to 17% of mice receiving dexamethasone only (P = 0.007)." (PMID 26967741, 2016). "Jude Total XV, patients with antibodies against asparaginase had a lower risk of developing osteonecrosis than those who did not develop antibodies." (PMID 26967741, 2016). "Thus, our study aimed to address the impact of asparaginase on osteonecrosis in a controlled, pre-clinical model." (PMID 26967741, 2016). "Additionally, despite efforts to mitigate osteonecrosis incidence with discontinuous use of glucocorticoids, there was no benefit realized which may have been attributed to an increased use in asparaginase therapy." (PMID 35844739, 2022). "Together, our data indicate the feasibility of achieving synergistic antileukemic effects with asparaginase and dexamethasone without an undesired increase in osteonecrosis using simple changes to the schedule of combination chemotherapy." (PMID 31059548, 2019). "The use of concurrent enrollment in the arms with and without asparaginase also allowed for control of inter-experimental variability in the incidence of osteonecrosis in mice." (PMID 31059548, 2019). "Here, we demonstrated that the addition of PEGylated asparaginase to a discontinuous dexamethasone regimen which mirrors contemporary delayed intensification/ reinduction therapy does not increase the incidence of osteonecrosis in the murine model." (PMID 31059548, 2019). "The addition of PEGylated asparaginase to discontinuous dexamethasone did not increase the rate of osteonecrosis in mice (10/36 in dexamethasone alone vs. 7/35 in dexamethasone with asparaginase combination, p = 0.62)." (PMID 31059548, 2019). "No mice in the control group or the asparaginase alone group developed either osteonecrosis or arteriopathy." (PMID 26967741, 2016). "In the present study, we did not observe any significant change in bone or vessels of mice receiving asparaginase alone, consistent with asparaginase enhancing the osteonecrotic effect of glucocorticoids, rather than a direct impact on osteonecrosis." (PMID 26967741, 2016). "However, despite this increased level of dexamethasone, asparaginase did not result in an increase in osteonecrosis above that observed with dexamethasone alone." (PMID 31059548, 2019).
thrombosis (13 papers, 2014 to 2024). "The combined effect of congenital thrombophilia and therapy with E. coli asparaginase and prednisolone increased the risk of thrombosis (OR 34.5 95% CI 4.39–271.42, p = 0.0008)." (PMID 35359904, 2022). "Only 5/22 (32%) of the patients suffered from thrombosis before the first dosing of asparaginase and the Cox regression analysis showed a clear association of asparaginase treatment with occurrence of truncal or CVL VTs (χ2: 6.850, P = 0.0089)." (PMID 28503810, 2017). "Despite these measures, 40% (8/20) of the catheter-associated thrombosis in the leukemic patients developed thrombosis in the temporal context of asparaginase medication." (PMID 25317335, 2014). "Additionally, longer duration of asparaginase at lower doses has been correlated with an increased risk of thrombosis." (PMID 35463883, 2022). "Venous thrombosis is another known adverse event of asparaginase, and one patient developed left upper limb deep venous thrombosis during our study period, but revascularization was achieved following anticoagulant treatment." (PMID 27093153, 2016). "Thus, we continued the use of asparaginase with anticoagulation therapy and closely monitored the patients when thrombosis occurred." (PMID 28000713, 2016). "No clear conclusion is available in the literature regarding whether further administration of asparaginase should be terminated when thrombosis occurs in adults." (PMID 28000713, 2016). "Asparaginase treatment is also associated with venous stasis and deep vein thrombosis in clinic and in animal models, although we did not observe such effects with asparaginase alone." (PMID 26967741, 2016).
acute myeloid leukemia (12 papers, 2016 to 2024). Acute myeloid leukemia (AML) is a group of neoplasms arising from precursor cells committed to the myeloid cell-line differentiation. "Among the hematological causes, it is mainly associated with acute myeloid leukemia (AML), especially acute promyelocytic (APL) and acute lymphoblastic (ALL), and especially when treated with asparaginase." (PMID 39768494, 2024). "Unexpectedly, recent work in acute myeloid leukemia found that asparaginase treatment was synthetically lethal with inhibition of GSK3." (PMID 33202731, 2020). "Asparaginase treatment has a relatively favorable toxicity profile and is licensed for acute myeloid leukemia." (PMID 33202731, 2020). "Asparaginase is an enzyme clinically used for the treatment of acute myeloid leukemia, and was previously reported to deplete glutamine availability in HEPG2 cells." (PMID 30176945, 2018). "It has been demonstrated in acute myeloid leukemia 15, chronic myeloid leukemia 16, and ovarian cancer cells 17 that asparaginase can induce apoptosis as well as autophagy, and asparaginase-induced tumor cell death could be enhanced by inhibiting autophagic process." (PMID 33391513, 2021). "This may be consistent with asparaginase-induced apoptosis being mediated by apoptosis-inducing factor (AIF), as has been reported for acute myeloid leukemia cells." (PMID 30578463, 2019).
Hyperglycemia (10 papers, 2014 to 2025). An increased concentration of glucose in the blood. "This study examined the prevalence of TH in a cohort of pediatric ALL patients and the impact on TH of type of steroid or asparaginase used and another risk factors for hyperglycemia such as age, gender, and overweight." (PMID 24734157, 2014). "Following that, the question that arises is: if transient hyperglycemia may be induced by the use of corticosteroids and asparaginase during the course of chemotherapy, what may be the cause of hyperglycemia in ALL patients observed prior to any therapy?" (PMID 29983896, 2018). "Endocrine dysfunctions like growth impairment, hyperglycemia, and adrenal insufficiency are common sequelae of corticosteroid and asparaginase exposure." (PMID 41373522, 2025). "Asparaginase-induced hyperglycemia can be explained by the fact that asparaginase decreases insulin production and insulin-receptor expression." (PMID 34640436, 2021). "The prevalence of hyperglycemia during ALL therapy has been reported to be 10% to 20% during treatment with asparaginase and corticosteroids, most frequently in children above 10 years of age, with resolution after cessation or tapering down of these drugs." (PMID 28413626, 2017). "Although this modification was instigated given a predominance of CNS relapse observed, hyperglycemia appeared to be the main toxicity that could be attributed to GC, while the remaining side effect profile appeared to be more related to asparaginase." (PMID 38867099, 2024). "GCS and asparaginase are the most frequent agents responsible for hyperglycemia." (PMID 36771416, 2023).
breast carcinoma (7 papers, 2016 to 2026). "Cell viability mean values in MCF-7 breast cancer cells using the developed GNPs-PEG-RGD-asparaginase system were reduced by a third, which were significantly lower than that resulting from the treatment with free asparaginase and Au NPs." (PMID 35744957, 2022). "Another member of the EAAT family, EAAT1, has been identified as a contributor to tumor initiation and progression, as well as asparaginase resistance in prostate cancer and breast cancer cells." (PMID 36457557, 2022). "In this regard, SLC1A3 (EAAT1) has been identified to contribute to asparaginase resistance in prostate and breast cancer in which combined treatment with asparaginase and EAAT1 chemical inhibition restrains cancer cell proliferation and tumor progression." (PMID 36457557, 2022). "Since, MTT assay results showed that purified asparaginase induced proliferation inhibition in human leukemic as well as human breast cancer cells, we were interested to test its toxicity on normal cells." (PMID 26891220, 2016). "Aminoadipate–semialdehyde synthase (AASS) is involved in amino acid metabolism and can influence responses to asparaginase and corticosteroids (both used in ALL treatment); otherwise, altered AASS expression has also been seen in breast cancer." (PMID 41379638, 2026). "We have used MTT assay to determine the cytotoxic effect of purified E. cloacae asparaginase on human leukemic cells HL-60, MOLT-4, and human breast cancer cells MDA-MB-231 and T47D." (PMID 26891220, 2016). "Generally, asparaginase may be beneficial for malignancies expressing low or no ASNS activity, and several studies have investigated the use of asparaginase in non-hematologic malignancies, such as pancreatic, ovarian, and breast cancers." (PMID 34277440, 2021).
acute pancreatitis (6 papers, 2022 to 2025). An acute inflammatory process that leads to necrosis of the pancreatic parenchyma. "The rates and nature of TEAEs of special interest (hypersensitivity, acute pancreatitis and embolic and thrombotic events) were consistent with the known safety profile of asparaginase." (PMID 40163215, 2025). "In isolation, asparaginase can be the primary culprit behind acute pancreatitis." (PMID 39011188, 2024). "However, some studies have been done in which asparaginase was reintroduced in select patient populations with mild acute pancreatitis who had complete resolution of symptoms." (PMID 39011188, 2024). "However, asparaginase is frequently discontinued due to its unique adverse effects, such as clinical allergy, subclinical hypersensitivity, acute pancreatitis, and thrombosis." (PMID 38888368, 2024). "The exact pathophysiology of acute pancreatitis with asparaginase is unknown." (PMID 39011188, 2024).
coagulation disorders (6 papers, 2014 to 2024). "Children with hematological malignancies are exposed to asparaginase and steroid induced coagulation defects." (PMID 24388573, 2014).
diabetes (6 papers, 2020 to 2025). "It would be interesting to explore whether therapeutic asparaginase could be utilized to prevent the induction or severity of colitis or delay the spontaneous development of diabetes in NOD mice mediated by islet-reactive CD4+ and CD8+ T cells." (PMID 40661510, 2025). "Given that asparaginase can be produced by Escherichia coli, our study may provide clues linking gut microbiota and diabetes." (PMID 33092635, 2020).
pancreatic cancer (6 papers, 2020 to 2025). "Two examples include the encapsulation of asparaginase and thymidine phosphorylase, which are proposed for pancreatic cancer and mitochondrial neurogastrointestinal encephalomyopathy patients, respectively." (PMID 38270470, 2024). "ERYTECH is conducting final clinical trials of erythrocytes loaded with asparaginase (Eryaspase) for the treatment of pancreatic cancer and triple-negative breast cancer." (PMID 32197542, 2020). "In addition, mouse models elucidate the oncogenic function of linc‐ZNF25‐1 and the enhanced therapeutic effect of asparaginase (L‐ASNase) in combination with GEM in pancreatic cancer." (PMID 40041969, 2025). "However, the impact of autophagy on pancreatic cancer under asparaginase induction has not been confirmed to date." (PMID 41316157, 2025). "Secondly, about half of pancreatic cancer patients exhibit absent or low expression of ASNS, which offers an opportunity for asparaginase’s clinical application in treating pancreatic cancer." (PMID 41316157, 2025).
acute leukemia (5 papers, 2024 to 2025). A clonal (malignant) hematopoietic disorder with an acute onset, affecting the bone marrow and the peripheral blood. "Three patients with a diagnosis of acute leukemia were using prothrombotic drugs; all three were taking corticoids (prednisone) and two were also taking asparaginase." (PMID 39306580, 2024). "This indicates that concentration of 0.1 μg/mL of Rylaze would provide a reasonable surrogate for clinically relevant plasma asparaginase activity in patients with acute leukemia." (PMID 38690164, 2024). "Asparaginase (ASNase) is a crucial part of acute leukemia treatment, but immune responses to the agent can reduce its effectiveness and increase the risk of relapse." (PMID 38686384, 2024). "While asparaginase sensitivity was not enhanced in normal hematopoietic progenitor cells, it was in various drug-resistant subtypes of acute leukemia due to Wnt pathway activation." (PMID 40240755, 2025).